MNDA (myeloid cell nuclear differentiation antigen)
Description:
May act as a transcriptional activator/repressor in the myeloid lineage. Plays a role in the granulocyte/monocyte cell-specific response to interferon. Stimulates the DNA binding of the transcriptional repressor protein YY1.
Synonyms: PYHIN3
Tractability: Antibody: its Gene Ontology location is reachable by antibodies, with high confidence. PROTAC: its protein half-life has been measured.
Gene: Protein-coding gene on chromosome 1 (158,831,332 to 158,849,506, forward strand). Ensembl gene ENSG00000163563.
Subcellular location: Nucleus; Cytoplasm
Subcellular location (Human Protein Atlas): Nucleoplasm; Cytosol; Nucleoli; Nucleoli rim; Vesicles
Pathways (Reactome):
Immune System: Neutrophil degranulation
Gene Ontology:
Molecular function: protein binding; double-stranded DNA binding
Biological process: B cell receptor signaling pathway; DNA damage response; negative regulation of B cell proliferation; positive regulation of apoptotic process; activation of innate immune response; cellular defense response; cellular response to interferon-beta
Cellular component: cytosol; extracellular exosome; nucleolus; nucleoplasm; azurophil granule lumen; extracellular region; ficolin-1-rich granule lumen; cytoplasm; nucleus
Genetic constraint (gnomAD): Loss-of-function variants: 40 observed, 33.45 expected, observed/expected ratio (o/e) 1.2, 90% interval 0.93 to 1.56. The upper end of that interval is the gene's LOEUF score, 1.56, which puts it in group 6 of 6, group 1 being the genes least tolerant of losing a copy. Missense variants: 482 observed, 450.86 expected, observed/expected ratio (o/e) 1.07, 90% interval 0.99 to 1.15. Synonymous variants: 169 observed, 164.72 expected, observed/expected ratio (o/e) 1.03, 90% interval 0.9 to 1.17.
Homologues: Orthologues: chimpanzee MNDA (99% identical), pig MNDA (58% identical), rabbit MNDA (56% identical), dog MNDA (55% identical), mouse Mndal (46% identical), rat Mnda (45% identical), mouse Ifi211 (41% identical), mouse Ifi205 (40% identical), mouse Ifi202b (25% identical). Paralogues in human: PYHIN1 (53% identical), IFI16 (51% identical), AIM2 (31% identical).